TNF (tumor necrosis factor)
Diseases named in the same sentence as TNF in open-access papers (continued):
Sharing a sentence is not in itself a finding about the gene and the disease.
Obesity (continued). "Within obese adipose tissue, increased expression of TNFα has been shown to reduce CD4+ T cell function, suggesting that obesity may also inhibit the function of CD4+ T cells early during breast tumorigenesis." (PMID 35435599, 2022). "Mohamad reported that administrate with withaferin A (1.25 mg/kg/d) for 12 weeks protected against high-fat diet induced obesity through reducing hepatic mRNA expressions of TLR4, NF-κB, TNF-α), chemokine (C-C motif) ligand-receptor, and cyclooxygenase 2 (COX2)." (PMID 35769384, 2022). "Moreover, obesity induced the activation of IFN, TNFα, IL-2 and IL-6 signaling in the aEC population." (PMID 36400935, 2022). "Indeed, lipopolysaccharide (LPS) challenge in rats with diet-induced obesity (DIO) resulted in an enhanced and prolonged fever in addition to an increase in circulating TNF-α and IL6." (PMID 35079937, 2022). "TNF-α and IL6 are two major pro-inflammatory factors in adipose tissue, and they are usually expressed at elevated levels in the serum and adipose tissue of obese individuals and involved in obesity-related systemic insulin resistance." (PMID 36501080, 2022). "Mme activation did not increase LPS-induced IL-6 or TNFα, suggesting that our innate immune memory model, and potentially weight cycling, is immunologically distinct from models of simple obesity." (PMID 36713396, 2022). "Tumor necrosis factor-α, plasma leptin, and non-esterified fatty acid levels are all high in obesity and can impact insulin resistance and consequently diabetes mellitus." (PMID 35845804, 2022). "In addition to influencing stem cell differentiation, the proinflammatory state that occurs in obesity increases the levels of cytokines that stimulate osteoclast formation and activity by affecting the RANKL/RANK/OPG pathway, such as TNF-α and IL-6." (PMID 35955431, 2022). "Obesity induces the secretion of inflammatory cytokines in adipose tissue, such as MCP-1 and tumour necrosis factor-α (TNF-α) via activation of the ERK, nuclear factor-κB (NFκB), and c-Jun N-terminal kinase (JNK) pathways, which contribute to ephrin-B1 downregulation." (PMID 35949596, 2022). "Insulin resistance, diabetes, obesity, and NAFLD are considered chronic inflammatory situations and there are numerous studies demonstrating a correlation between these groups of consequences and TNF-alpha." (PMID 36422507, 2022). "Markers of inflammation such as interleukin-1 beta (IL-1β), tumor necrosis alpha (TNF-α), monocyte chemoattractant protein-1 (MCP-1 or CCl-2), and interleukin 6 (IL-6), and markers related to obesity such as leptin and insulin were measured systemically in the blood." (PMID 36387539, 2022). "Periodontitis increased tumor necrosis factor-α level of lung tissues under LF, while IL-10 was not affected by obesity regardless of periodontitis." (PMID 36060644, 2022). "Furthermore, cytokines' release, such as tumor necrosis factor (TNF) and interleukin-6 (IL-6), is elevated, which is produced from the activated macrophages of the adipose tissue during obesity." (PMID 36304965, 2022). "In addition to TNF-α, other cytokines such as IL-1β and IFN-gamma are increased in obesity and DM2 and contribute to the impairment of the insulin signaling response." (PMID 36406408, 2022). "A clinical study revealed that obesity was firmly connected with various proinflammatory cytokines, such as interleukins (ILs: IL-5, -10, -12, and -13), interferon-γ (IFN-γ), and tumor necrosis factor-α (TNF-α), and obese patients displayed elevated plasma levels of IL-4, -10, and -13." (PMID 35267958, 2022). "By contrast, some reports have noted a negative correlation between cytokine levels (IL-6, adiponectin, and TNF-α) and obesity, suggesting that inflammation is a consequence of obesity rather than a contributing factor." (PMID 35682832, 2022).
Obesity (continued). "In human peripheral blood mononuclear cells (PBMCs), we did not detect significant differences in CD8 T cell frequency, GzmB, TNF, and IFN-γ expression between lean donors and donors with obesity, although there was a trend of reduced IFN-γ and GzmB expression in obesity." (PMID 35103755, 2022). "During obesity, adipocytes also function as endocrine cells and secrete adipokines, chemokines, and cytokines such as monocyte chemoattractant protein-1 (MCP-1) and TNF-α." (PMID 36517853, 2022). "Furthermore, TNF-α and IL-6 were more likely to be downregulated in DIO mice with periodontitis when compared with their obesity-only counterparts." (PMID 36060644, 2022). "Likewise, ADF appears to be ineffective for reducing plasma TNF-α, as two ADF trials in adults with overweight or obesity and metabolic syndrome, which tested changes in TNF-α have not demonstrated significant improvements following ADF regimens." (PMID 36296982, 2022). "Unlike TNF-α and IL-6, adiponectin’s serum concentrations decrease with obesity, and recent studies have shown that a high serum adiponectin also signifies a renal dysfunction." (PMID 35054932, 2022). "Obesity, combined or not with MetS, creates a higher risk of developing CKD, predisposing to a pro-inflammatory state, increased IL-6 and TNF-α and possible progression of kidney injury to terminal CKD." (PMID 35657982, 2022). "In this study, although inflammation due to obesity was not considered, the measurement of TNF-α indicates the spread of inflammation in liver tissue, which can also play a role in the regulation of hepatic MCP-1." (PMID 36110559, 2022). "Unhealthy lifestyle, e.g., obesity, smoking, and alcohol consumption increase concentrations of inflammatory markers, of which especially CRP, TNF-α and IL-6 may contribute to the development of insulin resistance and cardiometabolic diseases." (PMID 35831939, 2022). "The circulating levels of IL-6, IL-8, and tumour necrosis factor alpha (TNF-α) distinguished patients with obesity and lean controls but did not distinguish patients with and without NASH." (PMID 35887177, 2022). "Elevated TNF-α concentrations in OSAS and obesity may be playing a role in both the pathogenesis and consequences of both conditions." (PMID 36430593, 2022). "On the other hand, the absence of TNF-α reduced obesity-related markers in the kidney to varying degrees, thereby decreased glomerular and tubular damage, and mitigated renal fibrosis." (PMID 35054932, 2022). "Therefore, puerarin has the potential to treat obesity and its related complications by modulating ATM-induced inflammation by suppressing the TNF-α/NF-κB pathway." (PMID 35052852, 2022). "The fact that obesity-associated mediators do not induce S100A9 expression but TNFα and IL-1β do so, suggests an indirect mechanism for the increased S100A9 induction in dWAT and epidermis in the inflamed skin in obesity." (PMID 35198063, 2022). "Obesity leads to the induction of aromatase expression in adipose stromal cells (ASCs) and enhances estrogen levels as a result of increased COX-2 expression and elevated levels of proinflammatory mediators and cytokines: TNFα, IL-1, and IL-6." (PMID 36555323, 2022). "Furthermore, Tyzzerella was positively correlated with the majority of the obesity indicators, including body weight, liver weight, perirenal fat, mesenteric fat, TG, T-CHO, blood glucose, HOMA-IR, TNF-α, and IL-1β." (PMID 35548566, 2022). "Additionally, various studies said that tumor necrosis factor-alpha (TNF-α) was significantly raised among obese individuals, eventually rooted in IR, and surfaced the notion of an inflammatory element of obesity." (PMID 36105908, 2022). "TNF-alpha is the only cytokine, among those here described, to show an inverse trend suggesting a possible role in allergic asthma rather than in the asthma–obesity phenotype." (PMID 36291398, 2022).
Obesity (continued). "Accordingly, obesity is characterized by increased levels of circulating factors including insulin, insulin-like growth factor 1 (IGF-1), leptin, and inflammatory cytokines such as IL6 and TNFα." (PMID 36010901, 2022). "In contrast, obesity triggers the secretion of cytokines involved in osteoporosis, negative vessel remodeling, and inflammation with increased leukemia inhibitory factor (LIF), IL1β, CCL2, leptin, interferon gamma (IFNγ), IL6, and TNFα." (PMID 36010901, 2022). "The correlations between gut microbiota (based on OTUs) and obesity related indexes (including body weight gain, percent of epididymal fat weight, the levels of TG, TC, HDL, LDL, TNF-α, IL-6, IL-10, and IL-4) were investigated using the Pearson correlation analysis." (PMID 35807812, 2022). "A meta-analysis of the subjects’ inflammatory response data showed that training improved IL-6 levels and significantly reduced CRP levels in adolescents with obesity, but training did not improve TNF-α levels in adolescents with obesity." (PMID 36293806, 2022). "The suppressive effect of BSAn on NEFA release as well as TNFα and MCP-1 production, observed in this study, indicates that BSAn could be effective in alleviating obesity-related inflammation by reducing the cross-talk between macrophages and adipocytes." (PMID 34199668, 2021). "Likewise, FX supplementation (0.1 and 0.2%) prevented obesity development and reduced hyperglycemia in diabetic/obese KK-Ay mice, by supressing MCP-1 and TNF-α, which are involved in insulin resistance." (PMID 34677429, 2021). "Inflammatory signals, like IL-1β, TNF-α, IL-6, and TLR ligands, have all been shown to impact the HSC pool during acute and chronic inflammation and, interestingly, are also all elevated during obesity." (PMID 33554957, 2021). "Specifically, curcumin could regulate various molecular targets, such as nuclear factor κB (NF-κB), tumor necrosis factor-α (TNFα), and monocyte chemoattractant protein-1 (MCP-1), which might contribute to its therapeutic potential in obesity and diabetes." (PMID 33959308, 2021). "During obesity, macrophages switch to an activated state and secrete MCP-1 and TNF-α." (PMID 34248964, 2021). "In animal models of obesity and insulin resistance it was shown that the inhibition of FABP4 protein in macrophages reduces inflammatory cytokines (MCP-1, IL-1β, IL-6 and TNFα) and the formation of atherosclerotic lesions and foam cells and improves insulin sensitivity." (PMID 34834808, 2021). "In this study, we found that HIF-1α mediates MCP1, TNFα, and IFNγ production and that HIF-1α-mediated impairment of liver and EWAT increases IL-1β production, which induced M1 polarization in mice contributing to obesity-induced NAFLD." (PMID 34360607, 2021). "The hypothesis of this study is that individuals with obesity are more likely to have elevated leptin levels and inflammatory markers (including CRP, IL‐6, TNF‐α)." (PMID 33680494, 2021). "Moreover, various other fatty tissue products have been characterized, such as TNF-α, IL-6, IL-1, CCL2, and plasminogen activator inhibitor type-1, which play a crucial role in immune dysregulation in individuals with obesity." (PMID 34220807, 2021). "This review summarizes findings on the association of lung fibrosis with obesity, highlights the role of several critical inflammatory mediators (e.g., TNF-α, TGF-β, and MCP-1) in obesity related lung fibrosis and the implication of obesity in the outcomes of idiopathic pulmonary fibrosis patients." (PMID 35082682, 2021). "We further point to the possible link between TNF-α and CERK in obesity that could promote metabolic inflammation." (PMID 33859296, 2021). "Pro-inflammatory cytokines such as TNF-α, IL-1β, and IFN-γ dose- and time-dependently suppress adiponectin secretion by adipocytes, which probably accounts for the decreased plasma levels during chronic inflammation in obesity." (PMID 34639186, 2021).
Obesity (continued). "In accordance, elevated TNF-α and IL-6 independently predict incident HFpEF, the predominant type of HF in obesity and diabetes, but not HF with reduced ejection fraction (HFrEF)." (PMID 34671656, 2021). "Importantly, obesity-induced metabolic inflammation produces CRP, as a proinflammatory biomarker, and adipokines, including tumor necrosis factor-alpha (TNF-α) and interleukin (IL)-6, which further propagate inflammation." (PMID 34055004, 2021). "We have also observed similar findings in this study, whereby TNF-α, IL-6, IL-8, MIF and PIA-1 were significantly associated with OSA was independent of the degree of obesity." (PMID 34086720, 2021). "Increased levels of C-reactive protein (CRP), a serum acute-phase reactant produced by the liver, and other proinflammatory cytokines secreted by the adipose tissue such as interleukin-6 (IL-6) and tumor necrosis factor-α (TNF-α), have been reported in patients with obesity." (PMID 33919641, 2021). "As the focus of this study was to construct a systematic obesity-relevant metabolic network, we first checked the child’s clinical and biological parameters (leptin, OGTT insulin AUC, adiponectin, FFA, TNF-α, FPG, and total cholesterol) that are thought to be related to a change in BMI." (PMID 34946095, 2021). "In mice, HFD-induced obesity increased macrophage infiltration and expression of pro-inflammatory cytokines such as tumor necrosis factor α (TNF-α) and interleukin 6 (IL-6) in mesenteric WAT, and increased TNF-α expression in the gut." (PMID 34938153, 2021). "Tumor necrosis factor-alpha (TNFα) is one of many recognized physiological regulators of PAI-1 expression and may contribute to elevated plasma PAI-1 levels in sepsis and obesity." (PMID 34639132, 2021). "Obesity has been shown to be associated with the production of dysregulated cytokines and augment the synthesis of acute-phase reactants, such as IL-6, IL-8, TNF-α, C-reactive protein (CRP), and monocyte chemotactic protein-1 (MCP-1) in patients with obesity and various animal models of obesity." (PMID 34220807, 2021). "Therefore, the interaction between TNF-α and TGR5 expression was investigated in rats with high-fat diet (HFD)-induced obesity." (PMID 34357066, 2021). "The TNF-α-308A allele appears to modulate circulatory TNF-α levels and mitigate EDS independent of age, sex, obesity and OSA severity in adults with CAD." (PMID 34362196, 2021). "It is known that (pre)adipocytes, a predominant cell type present in the adipose tissues, express and secrete a variety of adipokines (leptin, adiponectin, etc.)as well as inflammatory cytokines (TNF-α, IL-1β, IL-6, etc.)and enzymes (iNOS, COX-2, etc.), which confer obesity inflammation." (PMID 34063048, 2021). "Besides adipokines, pro-inflammatory markers TNF-alpha and CRP have been shown to be disturbed in chronic diseases such as obesity and impaired glucoregulation." (PMID 33540682, 2021). "Furthermore, quercetin supplementation significantly suppressed the proinflammatory cytokines TNFα, IL-6, and MCP-1 levels in eWAT and sera, suggesting its ability to reduce obesity-induced adipose tissue and systemic inflammation." (PMID 33805912, 2021). "Similarly, in our previous study, we did not observe the significant differences between serum levels of CRP, TNF-α, IL-1, and IL-6 of girls with PCOS and normal weight compared to the group with overweight and obesity." (PMID 33849511, 2021). "Indeed, AMY1 was significantly decreased and the obesity-related salivary biomarkers resistin, MCP-1, TNF-α, IL-6 and CRP were significantly increased in overweight/obese children compared with normal weight children." (PMID 34444230, 2021). "HF+FO/E, but not HF+FO/D, was able to prevent the changes triggered by obesity in TNF-α, Il-10, and resistin secretion in ING and RP depots." (PMID 33652751, 2021).
Obesity (continued). "The study aimed to follow up on the changes in the peripheral CD4+ T lymphocytes and the pro-inflammatory cytokines; IL-6, TNF-alpha, MCP-1, and IL-10 at baseline and 12 weeks post-surgical intervention by the laparoscopic gastric sleeve (LGS) in morbidly obese patients (class III obesity subjects)." (PMID 33981153, 2021). "A mechanism study demonstrated that TNF-alpha and IL-6 can enhance HCC in NAFLD or obesity population, which could be activated by the elevated ER stress in NAFLD patients." (PMID 33868403, 2021). "TNF-α is a strong agonist for SERPINE1 expression and may contribute to elevated plasma levels in obesity, indeed high levels are considered to be biomarkers for T2DM55." (PMID 33446687, 2021). "In contrast, in our obesity model, genetic iron loading increased circulating TNFα levels in the dam but not in placentas or embryos, suggesting that maternal iron excess did modulate TNFα production." (PMID 34188052, 2021). "↑CD68 marker in obesity and in T2DM.↓CD11b, CD11c, CD163 and CD169 in T2DM patients↑TNFα, iNOS, IL-6, CD16, CD36, and CD206 in the T2DM Metformin restored TNFα, iNOS, IL-6, CD11c, CD36, CD169 and CD206 in T2DM patients to levels equivalent to those of lean volunteers." (PMID 34163481, 2021). "Concomitantly, markers of endothelial dysfunction correlated with cytokines levels of the Th1 immune orientation (IFNγ, TNFα), inflammation (IL-17a, MIP1α, G-CSF, TNFα, MIP1β, and IFNγ), and/or M1 activation (IL-6, IFNγ, TNFα, IP10, MIP1α, and MCP1), mostly in patients with obesity." (PMID 34038475, 2021). "Obesity, regardless of model, is marked by increased levels of a wide array of proinflammatory cytokines, like IL-6, TNF-α, and IL-1β, in the expanding tissues and circulation." (PMID 33554957, 2021). "PCOS is a low-grade inflammatory state; women with PCOS have higher levels of inflammatory markers such as C reactive protein (CRP), tumor necrosis factor α (TNF-α), and interleukin 6 (IL6), independent of associated obesity." (PMID 33746952, 2021). "TNF-α levels were increased in class II and III obesity groups." (PMID 32893859, 2020). "The anti-TNF treatment significantly reversed the obese phenotypes of TKO mice, indicating that TNF was a functional target of miR-17~92 family miRNAs in regulating obesity." (PMID 33150865, 2020). "Blood and tissue inflammatory cytokine levels including either TNF-α, IL-1b, IL-6, IL-10, or MIP-2a were also increased with obesity in 22 of 30 cases and may have contributed to inflammatory organ injury and worsened survival." (PMID 32211204, 2020). "Accordingly, the accumulation of macrophages results in the secretion of different proinflammatory mediators, such as interleukin (IL)-6 and tumor necrosis factor (TNF)-α, which can potentially contribute to the initiation and progression of obesity-induced metabolic complications." (PMID 32927712, 2020). "On the other hand, TNF-α levels were significantly increased in class II and III obesity groups only, while statistically no significant change has been noted at TNF-α levels in class I obesity in comparison with the normal subjects." (PMID 32893859, 2020). "As expected, the plasma levels of tumor necrosis factor α (TNFα) and leptin that were elevated in HFD-fed rats compared with those of normal rats in accord with a previous study showing that obesity and insulin resistance would increase the plasma level of proinflammatory cytokines and adipokines." (PMID 32098371, 2020). "When obese and non-obese carriers of studied genotypes were analyzed separately, obesity not TNF-α genotype was found to affect DNA damage as higher levels of DNA damage occurred in obese compared to non-obese." (PMID 30900134, 2020). "In obesity, WAT releases pro-inflammatory adipokines, such as tumor necrosis factor (TNF)-α, plasminogen activator inhibitor (PAI)-1, and monocyte chemoattractant protein (MCP)-1, which impair glucose metabolism due to the induction of low-grade systemic inflammation." (PMID 32012199, 2020).